FOLR1 (folate receptor alpha)
Diseases named in the same sentence as FOLR1 in open-access papers (continued):
Sharing a sentence is not in itself a finding about the gene and the disease.
tumor (continued). "Here, we describe a protease-activated anti-folate receptor 1 TCB (Prot-FOLR1-TCB) equipped with an anti-idiotypic anti-CD3 mask connected to the anti-CD3 Fab through a tumor protease-cleavable linker." (PMID 32581215, 2020). "The cell surface density of FOLR1, which is heterogeneous in any given tumor and between different tumors, is likely another critical parameter of the avidity effect that should be taken into consideration." (PMID 31497024, 2019). "For example, VPA affected the expression of P-glycoprotein (ABCB1) in tumor cell lines and in rat livers and that of folate receptor α (FRα; FOLR1) in pregnant mice and in a human placental cell line." (PMID 30298005, 2018). "By contrast, free FA would discount the anti-tumor capability by competitive binding to Folr1, which confirms the relationship between Folr1 and targeted treatment." (PMID 28416738, 2017). "The folate receptor (FOLR1) is known to be overexpressed in many tumor types including ovarian, breast, and lung, and this was also found in two of our EMC samples." (PMID 28423517, 2017). "Folr1-Ara-C durably impaired tumor growth as the tumor volumes remained the low levels throughout the treatment period." (PMID 28416738, 2017). "Folr1 targeted therapy attenuated the tumor growth and metastasis with down-regulation of MMPs proteins and activation of apoptosis." (PMID 28416738, 2017). "Since FOLR1 is widely over-expressed in almost all cancer cells, we selected folic acid as our tumor targeting ligand." (PMID 29296172, 2017). "The ratio correlated significantly with tumor type (p<0.0001) and identified FOLR1 to mediate the uptake in TC to LCNEC with an inverted ratio in SCLC, where SLC19A1 seems to mediate the folic acid uptake." (PMID 27064343, 2016). "For example, there is currently a clinical trial evaluating the potential for active tumor targeting using an injectable folate-fluorescein conjugate (EC17) to detect folate receptor alpha (FRA) positive lung tumors using an intra-operative imaging system." (PMID 27584018, 2016). "Nevertheless, epigenetic changes can offer a plausible explanation for elevated FOLR1 expression in some tumours." (PMID 27485273, 2016). "Of special note, however is, that a subgroup of type I cancers showing FOLR1 expression above median value 9.14 exhibited a far stronger sensitivity to platinum treatment than did the large majority of type I tumours." (PMID 27485273, 2016). "Since the initial tumor was a known pulmonary adenocarcinoma, which have upregulated levels of FOLR1, the patient was imaged using a folate fluorescein conjugated molecular imaging contrast agent." (PMID 25442640, 2014). "Kelemen discusses the significance of folate levels in tumor etiology and progression, with suggestions for future research in FOLR1 gene expression and regulation." (PMID 23319948, 2012). "Our tumor set also showed elevated expression of Folr1, which is a gene included in luminal epithelial gene expression cluster that is highly expressed in MMTV-PyMT, MMTV-Neu,and WAP-myc tumors." (PMID 19197353, 2009). "These tumors also showed high expression of Folate receptor 1 (Folr1), which is commonly up-regulated in luminal tumor mouse models." (PMID 19197353, 2009). "Folate receptor alpha (FRα) is another antigen expressed across multiple tumor types." (PMID 41012501, 2025). "Taken together, these findings indicate that the serum FOLR1 level may be a potential tumor marker for detecting HCC, especially in combination with AFP." (PMID 40038575, 2025). "Similarly, secreted phosphoprotein 1 (SPP1) from CAFs diminishes the effectiveness of tyrosine kinase inhibitors (TKIs) by upregulating folate receptor alpha (FOLR1) in tumor cells." (PMID 40507341, 2025). "Another promising agent, mirvetuximab soravtansine, an ADC targeting FRα, is most effective in tumours with FOLR1 overexpression, though resistance may arise if FRα expression is lost." (PMID 40141188, 2025).
tumor (continued). "Next, we analyzed the FOLR1 protein in tumor xenografts and patient tumor tissues." (PMID 39996761, 2025). "We were unable to detect T-cell expansion in our in vivo study using PDXs, which we hypothesize is likely due to lower disease burden at time of treatment, in addition to potential FH FOLR1-CART trafficking to active tumor sites." (PMID 40919994, 2025). "This decrease may be beneficial, as elevated FOLR1 levels correlate with aggressive tumor characteristics, diminished response to chemoradiotherapy, and poorer overall survival rates." (PMID 39949745, 2025). "Studies focusing on immune components within the tumor microenvironment could clarify FOLR1’s role in mediating interactions between cancer cells and immune compartments, providing valuable insights for selecting IMGN853 and immunotherapy combinations." (PMID 40029935, 2025). "FOLR1 was selected based on its secretory potential, and we thus examined whether tumor FOLR1 levels are reflected peripherally in HCC patients." (PMID 40038575, 2025). "In clinical practice, cases with 2+/3+ FOLR1 membranous staining in 65–85% of tumor cells fall within a borderline zone that may impact therapeutic eligibility for FRα-targeted agents." (PMID 40869006, 2025). "Prominent examples include HER2, TROP2, folate receptor alpha (FRα), glucose transporter 1 (GLUT1), and various angiogenic receptors, all of which are not only associated with tumor growth and survival but also correlate with poor prognosis and increased metastatic potential." (PMID 40871003, 2025). "Notably, primary HGSC tumor cells and metastatic omental epithelial cells demonstrated comparable FOLR1 expression levels." (PMID 40029935, 2025). "In vitro tumor cell killing in established patient-derived cell lines demonstrates antigen density–dependent cytotoxicity, with potent tumor cell killing in cell lines with increased FOLR1 expression." (PMID 40919994, 2025). "Twelve anti-FOLR1 candidates bound to tumor cells (bottom row)." (PMID 39594628, 2024). "We observed differences in FOLR1 expression by histological type, tumor grade and FIGO stage." (PMID 39596024, 2024). "In fact, FOLR1 is found in abnormal quantities in various epithelial tumors, including ovarian, lung, and breast cancer, enhancing the likelihood of ligand binding to the tumor." (PMID 39273288, 2024). "After tumor dissociation, we confirmed approximately 75% FOLR1 expression in the tumor cells." (PMID 38254822, 2024). "Furthermore, high FOLR1 expression was correlated with high tumor grade, nodule number, and FIGO stage." (PMID 38256120, 2024). "Among tested antigens, FOLR1 expression was most consistently detected in tumor cells." (PMID 38254822, 2024). "Previous studies have shown significant overexpression of FOLR1 in various tumor types of epithelial origin, including lung, pancreatic, colorectal, gastric, kidney, bladder, breast, ovarian, endometrial, testicular, brain and neck cancers, compared with cognate normal tissues." (PMID 38273401, 2024). "By selecting for high specificity, i.e., low off-target binding and reduced on-target off-tumor binding, we identified three candidates (anti-FOLR1 scFv-Fc 12, 14, and 19) with a staining profile similar to the established anti-FOLR1 positive reference antibody." (PMID 39594628, 2024). "More recently, novel molecular markers have been proposed, including HE4, CA 72-4, CA 19-9, folate receptor alpha (FRα), microRNA profiles, DNA methylation patterns, circulating tumour DNA and antibodies in liquid biopsies, particularly blood and cervical mucus and swabs." (PMID 38339123, 2024).
tumor (continued). "Three consecutive rounds of co-culture of CAR T cells with OV-90 target cells allowed for the identification of CAR candidates, which were able to mediate repeated killing of FOLR1-expressing cells as an in vitro surrogate approach for effective reduction of tumor burden." (PMID 39594628, 2024). "Here we report a Phase I dose escalation trial (NCT02546921) with the primary objective of exploring the safety and tolerability of MOv18 IgE, a chimeric first-in-class IgE antibody, in patients with tumours expressing the relevant antigen, folate receptor-alpha." (PMID 37491373, 2023). "Two of these tumor cell populations expressed EpCAM, FOLR1, and CD24 simultaneously." (PMID 37894472, 2023). "For example, folate receptor alpha (FRα) is highly expressed on many tumor cells as compared to healthy tissue and can be used as a targeting moiety to deliver therapeutics preferentially to the tumor." (PMID 37514019, 2023). "The FOLR1 level is much lower in mucinous tumors and in early tumor stages." (PMID 36233339, 2022). "Here, we found that Tandem CAR-T cells could specifically recognize either FOLR1- or MSLN-positive tumor cells and exhibited a superior antitumor effect with a lower E:T ratio than single-target CAR-T cells." (PMID 34803504, 2021). "We attribute this result to the induction of FOLR1 in tumor tissue." (PMID 33535554, 2021). "Interestingly, diffused FOLR1 expression was detected in MCF7 orthotopic xenograft tumor tissue (Figure 7d3,d4), although FOLR1 was scarcely detected in MCF7 cells in vitro by Western blotting analysis and RT-PCR." (PMID 33535554, 2021). "Interestingly, FOLR1 expression was detected diffusely throughout the MCF7 orthotopic xenograft tumor tissue (Figure 7e3,e4), although FOLR1 is scarcely detected by Western blot analysis or RT-PCR for in vitro MCF7 cells." (PMID 33535554, 2021). "For the expression of antigens in tumor tissues, the results indicated that the percentage of FOLR1+MSLN+ cancer cells was significantly decreased in the Tandem-CAR T cell group, while single-target CAR T cells only reduced the corresponding antigen level (p <0.0001)." (PMID 34803504, 2021). "However, in the orthotopic xenograft tumor mouse model, the growth of the MCF7 tumor was significantly suppressed despite a low FOLR1 expression level and resistance to MORAb-202 in vitro." (PMID 33535554, 2021). "FOLR1 was highly detected in T47D tumor tissue (Figure 6d3,d4)." (PMID 33535554, 2021). "However, targeting FOLR1 with TCBs resulted in on-target/off-tumor toxicity as FOLR1-TCBs can induce killing of normal cells with few hundred FOLR1 receptors." (PMID 32581215, 2020). "The results show that a relatively high concentration of folic acid functionalization of the nanostructured silica together with the incorporation of the cytotoxic tin fragment leads to an increase in the quantity of the soluble FOLR1 secreted by the tumour cells." (PMID 32503320, 2020). "The folate derivative, Folr1-targeted Ara-C could be transported into tumor cells by recognizing and combining with the unique Folr1 profile specifically." (PMID 28416738, 2017). "Thus, Folr1-Ara-C contributed more to anti-tumor activity regarding the proliferation, mobility and apoptosis." (PMID 28416738, 2017). "Representative microMRI scans for 3 distinct mice on every week showed that Folr1-Ara-C could enormously reduce the tumor burden, while faster tumor growth was found in the Ara-C administration group." (PMID 28416738, 2017). "Folr1 exhibited significant amounts of staining in human MB specimens and tumor cells." (PMID 28416738, 2017). "Selected examples include dendritic cell vaccines, patient-specific autologous tumor cell vaccines, and vaccines targeting various antigens enriched in tumor cells, such as folate receptor alpha, HER2, brachyury, insulin-like growth factor binding protein-2, survivin, and carcinoembryonic antigen." (PMID 28904804, 2017).
tumor (continued). "Especially, FOLR1 overexpression seems to be a tumor marker in a tissue-dependant manner and has gained interest for targeted therapies via antibodies (e.g. farletuzumab) or new folic acid-drug conjugates (e.g. vintafolide) for selective inhibition, which were tested in clinical trails." (PMID 27064343, 2016). "It is also unknown whether the relationship between folate status and survival varies by folate receptor alpha (FRα) expression of the tumor." (PMID 26970739, 2016). "Some discordance between mRNA and protein may also reflect heterogeneous expression of FOLR1 within the tumor." (PMID 25816016, 2015). "The tumor specificity of FOLR1 makes it a promising target for diagnosis and treatment strategies." (PMID 25816016, 2015). "Further staining of the tumor slides confirmed FOLR1 expression on the tumor cells." (PMID 25442640, 2014). "The expression of FOLR1 cannot be observed in normal endometrium tissue, suggesting that FOLR1 may serve as a good tumor cell surface marker for targeted therapy, and antibodies against FOLR1 may facilitate tumor-specific cellular uptake of molecular drugs." (PMID 23819113, 2013). "Optical imaging in humans has primarily involved imaging of vasculature and lymphatics using the non-specific, near-infrared dye indocyanine green, with more recent advances using fluorescent-labeled folate receptor-alpha targets for tumor-specific, fluorescence-assisted cytoreductive surgery." (PMID 22470501, 2012). "Moreover, FOLR1 was identified as a potential tumor suppressor and therapeutic target." (PMID 42122127, 2026). "Interestingly, for the pre-germline-reset parental antibody ETA-005, the reactivity against FOLR1 KO cells was already reduced in comparison to WT cells indicating that the molecular design itself already leads to an increased specificity towards cells expressing the tumor anchor FOLR1." (PMID 40755782, 2025). "Consequently, analysis of off-tumor binding of new CAR candidates targeting FOLR1 is important." (PMID 39594628, 2024). "In addition, excessive folic acid intakes could disrupt energy and lipid metabolism, promote tumour growth when cancer cells strongly express folate receptor alpha." (PMID 36816414, 2023). "As new immunotherapies and targeted therapies are revealed, our findings suggest value in further investigations into a panel of personalized tumor markers, which may include proteins with therapeutic relevance such as FOLR1, KRT19, KLK6, PARP-1, TROP2, and IFNL1." (PMID 34868557, 2021). "Therefore, we hypothesized that MORAb-202 specifically inhibits cell proliferation and tumor growth in FOLR1-positive cells, and its effect on cell cycle distribution is similar to that of eribulin, which is a payload of MORAb-202." (PMID 33535554, 2021). "Interestingly, in orthotopic xenograft mouse models, not only was the FOLR1-expressing T47D tumor suppressed upon MORAb-202 administration but the non-FOLR1-expressing MCF7 tumor was also completely suppressed; we attribute the latter result to the induction of FOLR1 in vivo." (PMID 33535554, 2021). "S. Karagiannis (King’s College, UK) investigated in her presentation “Mechanisms of action for MOv18 IgE targeting folate receptor alpha-expressing tumours” whether antibodies engineered with Fc regions of IgE class may provide an alternative approach for treating solid tumours." (PMID 30867007, 2019). "Moreover, only tumor-associated Folr1 can be accessible to FA in the circulation, but not the normal Folr1." (PMID 28416738, 2017). "Functional assays showed that FOLR1 was significantly downregulated in LUAD tissues and cell lines; FOLR1 knockdown promoted tumor cell proliferation, whereas restoration of its expression or pharmacological intervention markedly suppressed tumor progression." (PMID 42122127, 2026). "One study reported that FOLR1-specific CAR-T cells effectively recognized and lysed FOLR1-positive GC cells, inducing cytotoxicity and subsequent tumor cell death." (PMID 40977703, 2025).
tumor (continued). "The folate receptor α (FRα), also known as FOLR1 or folate-binding protein, is a cysteine-rich glycoprotein pivotal in tumor growth and metastasis, mediating folate transport via receptor-endocytosis." (PMID 40050918, 2025). "The tissue consisted of 24% pan-CK–positive tumor cells, which expressed FOLR1 and CD277 (BTN3A), 49% CD45-positive leukocytes, and 27% tumor-surrounding cells (including stromal and epithelial cells)." (PMID 40755782, 2025). "designed a novel third-generation TanCAR targeting both FOLR1 and MSLN, combined with IL-12 secretion, to reduce the likelihood of tumor antigen escape and enhance CAR-T cell infiltration and antitumor activity." (PMID 40092990, 2025). "Two genes FOLR1 and TNS4 exhibit context-dependent roles in cancer, acting as oncogenes or tumor suppressors depending on tissue type and expression levels." (PMID 41439026, 2025). "We determined the expression of the FOLR1 gene in a broad range of GCT cell lines and tumor xenografts." (PMID 39996761, 2025). "Remarkably, within just 2 hours, MB49 tumor cells exhibited notable uptake of BTO-CPT/FA, primarily due to the high expression of folate receptor alpha on the MB49 tumor cell surface, which facilitates the effective uptake of folate-conjugated NPs." (PMID 41253767, 2025). "Antigen-specific IgE antibodies against targets like folate receptor alpha (FRα) and HER2/neu have shown enhanced anticancer efficacy by engaging FcεR-expressing effector cells in the tumor microenvironment." (PMID 41567205, 2025). "The penetration depth of FOLR1-directed CAR T cells was significantly increased, indicating that anti-FOLR1 CAR T cells can infiltrate into a three-dimensional structure and lyse the respective tumor cells." (PMID 38254822, 2024). "Microscopic analysis demonstrated that positive expression of FOLR1 and FOLR2 proteins in tumor cells was present in 48 (82.76%) and 41 (70.69%) out of 58 patients, respectively." (PMID 38915965, 2024). "This is in contrast to the OV-90 Mock and the untreated group as well as the OV-90 FOLR1 KO xenograft groups, which were composed primarily of GFP-expressing tumor cells." (PMID 38254822, 2024). "At the end of co-culture with anti-FOLR1 CAR T cells, patient-derived tumor cells were completely lysed." (PMID 38254822, 2024). "Thereby, we concluded that anti-FOLR1 CAR candidates A and E performed best in vivo, indicated by rapid tumor eradication, pronounced proliferation, CAR expression, and short-term persistence." (PMID 38254822, 2024). "Taken together, anti-FOLR1 CAR T cells can infiltrate into OvCa spheroids and are functional against patient-derived tumor cells in the presence of malignant ascites." (PMID 38254822, 2024). "Second, we assessed the functionality of our FOLR1-specific CAR T cells against patient-derived tumor cells in an autologous setup, i.e., tumor cells, CAR T cells, as well as ascites derived from the same patient." (PMID 38254822, 2024). "One of the tumor cell populations, CD45−CD56−(EpCAM+FOLR1+CD24+), demonstrated high expression of the markers." (PMID 37894472, 2023). "The folate receptor alpha (FR), which is overexpressed in solid tumors including NSCLC, can be utilized for active tumor targeting to afford more effective cancer therapies." (PMID 35335867, 2022). "EPCAM+/FOLR1- cells had a larger proportion in tumor samples, while there were more EPCAM-/FOLR1+ cells in normal lung tissues." (PMID 36249427, 2022). "Herein, using bioinformatics and clinical samples, we identified two candidate proteins, folate receptor 1 (FOLR1) and mesothelin (MSLN), that were highly expressed in tumor tissues but exhibited low expression in normal tissues." (PMID 34803504, 2021).